RN7SL159P (RNA, 7SL, cytoplasmic 159, pseudogene)
Gene: Miscellaneous RNA gene on chromosome 9 (129,370,170 to 129,370,461, reverse strand). Ensembl gene ENSG00000242281.
Homologues: Orthologues: chimpanzee Metazoa_SRP (97% identical), macaque Metazoa_SRP (92% identical). Paralogues in human: RN7SL1 (81% identical), RN7SL2 (80% identical), RN7SL3 (80% identical), RN7SL444P (79% identical), RN7SL769P (78% identical), RN7SL45P (78% identical), RN7SL122P (78% identical), RN7SL336P (78% identical), RN7SL448P (78% identical), RN7SL322P (77% identical), RN7SL19P (77% identical), RN7SL357P (77% identical), and 701 more.